RXFP4 (relaxin family peptide/INSL5 receptor 4)
Description:
High affinity receptor for INSL5. Also acts as a receptor for RLN3/relaxin-3, as well as bradykinin and kallidin. Binding of the ligand inhibit cAMP accumulation.
Synonyms: GPCR142; GPR100; RLN3R2; RXFPR4
Tractability: Small molecule: a structure with a bound ligand is known; it belongs to a druggable protein family. Antibody: its Gene Ontology location is reachable by antibodies, with high confidence; UniProt places it where antibodies can reach, with medium confidence; UniProt predicts a signal peptide or a membrane-spanning region. PROTAC: a small molecule that binds it is known.
Target class: Relaxin receptor; Relaxin-like peptide receptor (family A GPCR); Family A G protein-coupled receptor; Peptide receptor (family A GPCR); Membrane receptor
Gene: Protein-coding gene on chromosome 1 (155,941,638 to 155,943,087, forward strand). Ensembl gene ENSG00000173080.
Subcellular location: Cell membrane
Pathways (Reactome):
Signal Transduction: G alpha (i) signalling events; Relaxin receptors
Gene Ontology:
Molecular function: protein binding; galanin receptor activity; G protein-coupled receptor activity
Biological process: neuropeptide signaling pathway; G protein-coupled receptor signaling pathway
Cellular component: plasma membrane; membrane
Genetic constraint (gnomAD): Loss-of-function variants: 0 observed, 0.0866 expected, observed/expected ratio (o/e) 0, 90% interval 0 to 1.89. That is too few expected variants to judge how well the gene tolerates losing a copy. Missense variants: 425 observed, 503.85 expected, observed/expected ratio (o/e) 0.84, 90% interval 0.78 to 0.91. Synonymous variants: 182 observed, 220.63 expected, observed/expected ratio (o/e) 0.82, 90% interval 0.73 to 0.93.
Homologues: Orthologues: chimpanzee RXFP4 (99% identical), pig RXFP4 (87% identical), mouse Rxfp4 (75% identical), Caenorhabditis elegans npr-17 (22% identical). Paralogues in human: GPR25 (25% identical), AGTR2 (24% identical), APLNR (23% identical), BDKRB1 (23% identical), AGTR1 (22% identical), BDKRB2 (21% identical), GPR15 (19% identical).
Diseases named in the same sentence as RXFP4 in open-access papers:
RXFP4 is named in the same sentence as 18 diseases in open-access papers, as found by Europe PMC text mining. Sharing a sentence is not in itself a finding about the gene and the disease. The quoted sentences say what the papers report.
Obesity (2 papers, 2019 to 2023). Accumulation of substantial excess body fat. "Finally, these observations suggest that the modulation of the INSL5/RXFP4 axis might represent a target for the treatment of obesity in humans." (PMID 37297947, 2023).
acute leukemia (1 paper, 2017). A clonal (malignant) hematopoietic disorder with an acute onset, affecting the bone marrow and the peripheral blood. "Multivariate linear regression analysis revealed that female sex, diagnosis of acute leukemia, history of multiple chemotherapy regimens, and RXFP4 genotype (TT and TA) remained independently associated with lower circulating CD34+ cell count after mobilization in the Korean set." (PMID 28666004, 2017).
breast carcinoma (1 paper, 2020). "Rxfp4 was expressed in all three human cancer cell lines, Jurkat, MCF-7 and SupT, while Insl5 was also expressed in the latter two, with both genes showing the highest expression in the breast cancer MCF-7 cells." (PMID 33519716, 2020).
colorectal adenocarcinoma (1 paper, 2023). The most common type of colorectal carcinoma. "In addition, we used a cell model to study RXFP4 signalling in vitro by modulating RXFP4 levels in a human colorectal adenocarcinoma cell line (Colo320) that has been shown to express TPH1 and secrete 5-HT." (PMID 36947541, 2023).
colorectal NETs (1 paper, 2025). "All examined rectal NETs co-expressed INSL5 and RXFP4, suggesting that INSL5-RXFP4 signaling could be involved in the biology of colorectal NETs." (PMID 41458541, 2025).
cryptorchidism (1 paper, 2020). The failure of one or both testes of a male fetus to descend from the abdomen into the scrotum during the late part of pregnancy. "INSL3 and RXFP4, two genes encoding a ligand–receptor pair implicated in cryptorchidism (absence of testes from the scrotum due to their failure to descend), are lost in several Afrotheria that have naturally lost testicular descent." (PMID 33575564, 2020).
Infertility (1 paper, 2022). "RXFP4 expression in the testes of INSL5-deficient mice resulted in infertility due to irregular length of the oestrous cycle and spermatogenesis disorders." (PMID 36303231, 2022).
neuroendocrine tumors (1 paper, 2020). "Studies have reported that RXFP4 was involved in the regulation of human neuroendocrine tumors." (PMID 33282942, 2020).
rectal NETs (1 paper, 2025). "In the context of NEC metabolic biomarkers, INSL5 and its receptor RXFP4 have been identified in colorectal tissues and may play a role in rectal NETs." (PMID 41458541, 2025).
cancer (2 papers, 2020). A tumor composed of atypical neoplastic, often pleomorphic cells that invade other tissues. "Turning to mouse and human cell lines, we found that Rxfp4 was expressed in both mouse macrophage cell lines (ANA-1 and BALB/c), as well as three human cancer cell lines (Jurkat, MCF-7, and SupT)." (PMID 33519716, 2020).
tumor (2 papers, 2020 to 2021). "Whilst the expression of RXFP4 was significantly lower in the tumor tissues (p < 0.001), the RXFP4 mRNA level was still maintained at a high level." (PMID 34419055, 2021). "The differential expression of RXFP4 mRNA between the tumor and normal tissue may not be the major factor for CRC prognosis." (PMID 34419055, 2021).
RXFP4 also shares sentences with these, for which no sentence is quoted: Anxiety (1 paper); Crohn disease (1); diabetes (1); metabolic disorders (1); metabolic syndrome (1); nasopharyngeal carcinoma (1); rectal neuroendocrine tumor (1).